MAP1LC3B (microtubule associated protein 1 light chain 3 beta)
Diseases named in the same sentence as MAP1LC3B in open-access papers (continued):
Sharing a sentence is not in itself a finding about the gene and the disease.
depression (6 papers, 2021 to 2025). "The results of the present study show that the expressions of autophagy‐related genes (Fkbp5, Mmp9, and Map1lc3b) were increased in the hippocampus of a mouse model of depression that exhibited weight loss." (PMID 39715728, 2025). "In the hippocampus, the expression levels of Fkbp5, Mmp9, and Map1lc3b were significantly higher in CIS‐depression model mice than in control mice." (PMID 39715728, 2025). "In the present study, Fkbp5, MMP9, and Map1lc3b mRNA expressions were upregulated in the depression model mice compared with the control mice." (PMID 39715728, 2025). "The expression of autophagy‐related genes (Atg5, Atg7, Atg12, Becn1, Mmp9, Fkbp5, and Map1lc3b), which are reported to be upregulated in the brains of MDD patients, were examined in the hippocampus and midbrain of control and depression model mice." (PMID 39715728, 2025).
preeclampsia (6 papers, 2017 to 2021). Preeclampsia is a hypertensive disorder of pregnancy that is characterized by new-onset hypertension with proteinuria presenting after 20 weeks of gestation, and depending on mild or severe forms may initially present with severe headache, visual disturbances, and hyperreflexia. "There was a significant difference between these groups in the MAP1LC3B/BECN1 ratio as marker of the trophoblast survival capacity with a significantly reduced ratio in villous trophoblast of early-onset preeclampsia." (PMID 30408071, 2018). "Serum and placental samples from four groups of cases; normal term, IUGR, early-onset and late-onset preeclampsia, were analyzed for 25(OH)D vitamin D, sFLT1, PGF, LGALS13 in serum and vitamin D receptor (VDR), MAP1LC3B and BECN1 in placental tissues." (PMID 30408071, 2018). "Furthermore, there was a strong and significant correlation between the MAP1LC3B/BECN1 ratio as survival marker and VDR levels in the early-onset preeclampsia group." (PMID 30408071, 2018).
thyroid cancer (6 papers, 2015 to 2025). "Five hundred and sixty-seven miRNAs associated with nine autophagy proteins (ULK1, ATG16L1, MAP1LC3B, PRKAA1, ATG12, ATG 14, ATG5, mTOR and BECN1) were identified, of which sixty-two are accompanied by thyroid cancer, and only miR-125b is associated with the autophagy modulation in this pathology." (PMID 36980957, 2023). "To better understand the role of LINC00162 in thyroid cancer progression, we evaluated the expression of the autophagy-related genes ATG5, ATG7, and MAP1LC3B." (PMID 40804316, 2025). "To investigate the impact of LINC00162 knockdown and sorafenib treatment on autophagy in thyroid cancer cells, we analyzed the expression levels of ATG5, ATG7, and MAP1LC3B genes in B-CPAP cancer cells." (PMID 40804316, 2025).
Alzheimer disease (5 papers, 2018 to 2025). A progressive, neurodegenerative disease characterized by loss of function and death of nerve cells in several areas of the brain leading to loss of cognitive function such as memory and language. "Among the genes highlighted in the network analysis, four were also confirmed in the Alzheimer’s disease animal models: ATG3, GABARAPL2 (ATG8), MAP1LC3B, and SQSTM1." (PMID 30850634, 2019).
liver cancer (5 papers, 2016 to 2025). An epithelial or non-epithelial malignant neoplasm that arises from the liver. "Map1LC3B, a structural component of autophagosomes, was up-regulated by panobinostat in liver cancer cells and in mice xenografts." (PMID 27058414, 2016).
lung fibrosis (5 papers, 2020 to 2025). "Studies have shown that microtubule-associated protein 1 light chain 3 beta (LC3B) expression is downregulated in lung fibrosis tissues of patients, indicating autophagy activity is decreased." (PMID 36267283, 2022).
steatosis (4 papers, 2020 to 2023). Increased lipid within the cytoplasm of cells. "Of particular interest in this respect, PHH with FFA-induced steatosis displayed a decrease in the expression of the genes encoding microtubule associated proteins 1A/1B light chain 3 beta (LC3; also known as MAP1LC3B) and sirtuin-1 (SIRT1), two markers of autophagy activation." (PMID 32094147, 2020).
colon adenocarcinoma (3 papers, 2021 to 2025). "Our microarray data show DJ-1 mRNA expression was positively correlated with MAP1LC3A and MAP1LC3B expressions in tumor tissues from subjects with colon adenocarcinoma." (PMID 34439303, 2021). "The analysis results of GEPIA (Gene Expression Profiling Interactive Analysis) show DJ-1 mRNA expression was positively corrected with MAP1LC3A and MAP1LC3B expressions in tumor tissues of subjects with colon adenocarcinoma (R = 0.41 in both two)." (PMID 34439303, 2021). "We analyzed the correlation between KRAS mutational status and expression of several autophagy genes, including MAP1LC3B, ATG5, ATG10, ATG13, and ATG14 in both COAD (colon adenocarcinoma) READ (rectum adenocarcinoma) as well as normal tissue." (PMID 39057088, 2024).
gastric adenocarcinoma (3 papers, 2017 to 2021). "We demonstrate that gastrin increases the expression of the autophagy markers MAP1LC3B-II and SQSTM1 in gastric adenocarcinoma cells." (PMID 28109268, 2017).
osteoporosis (3 papers, 2022 to 2025). A condition of reduced bone mass, with decreased cortical thickness and a decrease in the number and size of the trabeculae of cancellous bone (but normal chemical composition), resulting in increased fracture incidence. "This study identified PDPK1, MAP1LC3B, ZFP36, DRAM1, and MPO as potential biomarkers and proposes a nomogram based on hub genes for predicting osteoporosis risk." (PMID 39791175, 2025).
Parkinson disease (3 papers, 2021 to 2025). A progressive degenerative disorder of the central nervous system characterized by loss of dopamine producing neurons in the substantia nigra and the presence of Lewy bodies in the substantia nigra and locus coeruleus. "It has been shown that overexpression of miR-133a inhibits MPP+-induced autophagy (MAP1LC3A/MAP1LC3B, BECN1, NUP62) in a cellular model of Parkinson’s disease, and downregulation of miR-17-5p inhibits infarction-induced myocardial autophagy." (PMID 36324052, 2023).
psoriasis (3 papers, 2022 to 2025). An autoimmune condition characterized by red, well-delineated plaques with silvery scales that are usually on the extensor surfaces and scalp. "Mice lacking the MAP1LC3B protein did not exhibit the improvement in imiquimod-induced psoriasis brought on by the andrographolide compound." (PMID 38712377, 2025).
renal carcinoma (3 papers, 2016 to 2024). A carcinoma arising from the epithelium of the renal parenchyma or the renal pelvis. "Here, we describe a high content screen from which we identified small chemical compounds that can modulate the localization of the autophagy marker MAP1LC3B (LC3) in renal carcinoma cells." (PMID 29944143, 2018).
B cell lymphoma (2 papers, 2020 to 2021). "The DNA methylation of CpG island causes the reduction of miR-342-3p, which is resulted in failure to operate tumor suppressor function by inhibiting pro-survival autophagy by targeting MAP1LC3B and DNMT1 in B cell lymphoma." (PMID 34526970, 2021).
carotid atherosclerosis (2 papers, 2014 to 2020). A thickening and loss of elasticity of the walls of carotid arteries that occur with formation of atherosclerotic plaques. "mRNA levels of MAP1LC3B, a marker of carotid atherosclerosis, were significantly decreased in extracts from full carotid plaques from symptomatic patients (p < 0.0001)." (PMID 33317170, 2020).
COVID-19 (2 papers, 2021 to 2022). A disease caused by infection with severe acute respiratory syndrome coronavirus 2. "More LC3B- and particularly P62-positive cells were identified in COVID-19 patient lung samples, which might be explained by increased MAP1LC3B and SQSTM1 mRNA levels or again by a reduced autophagic flux and protein accumulation." (PMID 34155207, 2021).
Hermansky-Pudlak syndrome (2 papers, 2023 to 2024). Hermansky-Pudlak syndrome (HSP) is a multi-system disorder characterized by oculocutaneous albinism, bleeding diathesis and, in some cases, neutropenia, pulmonary fibrosis, or granulomatous colitis. "Microtubule Associated Protein 1 Light Chain 3 Beta (MAP1LC3B) is linked with conditions such as Hermansky-Pudlak Syndrome and Granulomatous Disease." (PMID 38388661, 2024).
lupus (2 papers, 2022 to 2025). "Finally, we verified the expression of TNFSF10 and MAP1LC3B in a lupus mice model." (PMID 39869603, 2025).
periodontal disease (2 papers, 2022 to 2025). "This study reveals the high-expression of VPS13C and MAP1LC3B in periodontal disease and their potential association with mitophagy, suggesting that they may serve as novel targets for regulating chronic inflammation and mitochondrial homeostasis." (PMID 40859550, 2025). "One possibility is that the upregulation of VPS13C and MAP1LC3B in periodontal disease may inhibit mitophagy, thereby exacerbating OS and leading to further tissue destruction." (PMID 40859550, 2025).
periodontitis (2 papers, 2024 to 2025). An acute or chronic inflammatory process that affects the tissues that surround and support the teeth. "The results pertaining to mitophagy-related markers indicated that the expression levels of mitophagy pathway-related genes (Bnip3 and Fundc1) and autophagy-related genes (Map1lc3a and Map1lc3b) were significantly upregulated in the periodontitis+TTM group when compared with the periodontitis group." (PMID 38892077, 2024). "BNIP3L and CTTN were downregulated in periodontitis, correlating negatively with disease prevalence, immune infiltration, and inflammatory pathways, whereas VPS13C and MAP1LC3B were upregulated, showing positive correlations." (PMID 40859550, 2025).
Atrophy (1 paper, 2025). Any weakening or degeneration, especially through lack of use. "Recent work also identified Nestin as a critical regulator of autophagy-dependent ferroptosis in muscle atrophy; Nestin interacts with MAP1LC3B (LC3B), catalyzing its polyubiquitination to inhibit autophagy flux and suppress ferroptosis, whereas Nestin knockout exacerbates atrophy." (PMID 41334559, 2025).
autism (1 paper, 2016). Persistent deficits in social interaction and communication and interaction as well as a markedly restricted repertoire of activity and interest as well as repetitive patterns of behavior. "Four genes in our candidate list for autism (MAP1LC3B, PDE4B, TCF4 and UPF2) have already been associated with ASD." (PMID 26731442, 2016). "The first network included 15 Root 66 genes, 2 of them already associated with autism (MAP1LC3B and PDE4B), that interact in neurological processes involved in normal brain growth and function, such as formation of astrocytes, proliferation of cortical neurons, sorting of axons and myelination." (PMID 26731442, 2016). "Four of the Root 66 genes (MAP1LC3B, PDE4B, TCF4 and UPF2) have previously been associated with autism, and 56 either have been shown to interact directly with known autism candidates or have been implicated in other autism-related neurological disorders." (PMID 26731442, 2016).
GEJ adenocarcinoma (1 paper, 2021). "We examined the levels of three autophagy-related proteins, MAP1LC3B (LC3B), p62, and LAMP2A, by IHC in the normal-to-carcinoma spectrum, and we describe their heterogeneous expression patterns in our cohort of gastric/GEJ adenocarcinoma." (PMID 33859932, 2021).
invasive ductal carcinoma (1 paper, 2021). "Using a tissue microarray from 274 breast invasive ductal carcinoma (IDC) patients, we found that tumor tissues showed higher protein levels of MAP1LC3B and cytoplasmic SQSTM1 in comparison to those in adjacent normal tissues." (PMID 34829743, 2021).
malaria (1 paper, 2019). Malaria is a serious and sometimes fatal disease caused by a parasite that commonly infects a certain type of mosquito which feeds on humans. "Interestingly, the malaria pigment, hemozoin (HZ),—showed a moderate negative correlation with the mRNA levels of the three genes: ULK1 (rs = -0.57, P < 0.0001), BECN1 (rs = -0.40, P = 0.0088), and MAP1LC3B (rs = -0.42, P = 0.0053)." (PMID 31805150, 2019).
metastatic tumors (1 paper, 2024). "For example, recent studies have shown punctate staining or increased expression of microtubule-associated protein 1 light chain 3 beta (LC3B) in various metastatic tumors, suggesting that autophagy is upregulated during metastasis." (PMID 38861187, 2024).
pancreatic insulinoma (1 paper, 2023). An insulin-producing neuroendocrine tumor arising from the beta cells of the pancreas. "In particular, pancreatic insulinomas (n = 24) showed a higher expression of the autophagic genes BECN1 (p < 0.001), MAP1LC3B (p < 0.001), SQSTM1 (p = 0.008), TFEB (p < 0.001), PRKAA1 (p = 0.038), and PRKAA2 (p = 0.019) compared to NF-pNET (n = 7)." (PMID 36835048, 2023).
SARS-CoV infections (1 paper, 2022). "It was found that 45.87% of the associated genes (CASP3, CASP9, MAPK1, MAPK3, XIAP) contributed to cytochrome C-mediated apoptotic response and 3.67% of the associated genes (BECN1, FXYD2, GSK3B, HSP90AA1, ITGB1, MAP1LC3B) contributed to SARS-CoV infections." (PMID 36164436, 2022).
schizophrenia (1 paper, 2024). A major psychotic disorder characterized by abnormalities in the perception or expression of reality. "Finally, we identified CSNK2B, TOMM40, MAP1LC3B, MFN1, CSNK2A2, PGAM5 and ATG12 as the diagnostic genes for schizophrenia." (PMID 39355378, 2024).
tumor (297 papers, 2012 to 2026). "ATG12, BECN1 and MAP1LC3B (Microtubule-associated proteins 1A/1B light chain 3 B) were reported to be associated with the three autophagy-related lncRNA through analysis in Tumor Immune Estimation Resource (TIMER), Oncomine and Human Protein Atlas Database." (PMID 38291202, 2024). "Treatment with panobinostat caused a massive increase in the expression of Beclin1 and Map1LC3B in HepG2 tumor xenografts." (PMID 27058414, 2016). "Moreover, high MAP1LC3B levels are associated with reduced tumor aggressiveness in early-stage NSCLC." (PMID 34829743, 2021). "Results showed that KPC tumor-induced increase in the mRNA levels of Fbxo32, Trim63, Map1lc3b, Cd36, Acox3, and spliced-Xbp1 (sXbp1) in skeletal muscle were significantly reduced by treatment of mice with 4μ8C." (PMID 40655023, 2025). "More relevant, the stratification based on MAP1LC3B expression shows that the patients with a tumor expressing high MAP1LC3B survive longer than low-expressers (p = 0.0120)." (PMID 39519080, 2024). "In the tumor-bearing vehicle-treated group, we observed a significant increase in relative transcript levels of Sqstm1, Map1lc3b, and Becn1 compared to all tumor-free groups (p < 0.0001 for all comparisons)." (PMID 33718372, 2021). "The tumor suppressor function of miR-342-3p was mediated via inhibition of pro-survival autophagy by targeting MAP1LC3B and downregulation of DNMT1 with demethylation and re-expression of tumor suppressor genes." (PMID 33076962, 2020). "Here, we showed that the expression levels of VHL and microtubule-associated protein 1 light chain 3B (MAP1LC3B, LC3B) were inversely correlated with various tumor grades of RCC tissues." (PMID 30902965, 2019). "The autophagy marker microtubule-associated protein light chain 3B (MAP1LC3B) and adaptor sequestosome 1(SQSTM1) are widely used proteins to evaluate autophagy in tumor tissues." (PMID 30477228, 2018). "SQSTM1 expression was positively correlated with MAP1LC3B expression in tumor tissues of patients with BMSCC." (PMID 30477228, 2018). "Beclin1 and Map1LC3B expression was analyzed by immunohistochemistry in HepG2 tumor xenografts in mice that had been treated for 4 weeks with 10 mg/kg panobinostat." (PMID 27058414, 2016). "Interrogation of a TCGA dataset led to the conclusion that patients bearing a tumor with low expression of such Hh/EMT genes along with high expression of the MAP1LC3B gene (suggestive of active autophagy) have a better overall survival and are more responsive to platinum-based therapy." (PMID 34831435, 2021). "Also, the mRNA levels of Map1lc3b and Sqstm1 were upregulated in tumor hosts, together with increased Ctsl1 and Lamp2 gene expression." (PMID 30823492, 2019). "We further determined whether MAP1LC3B expression was correlated with SQSTM1 in tumor tissues and adjacent normal tissues in three subsites of OSCC." (PMID 30477228, 2018). "Nevertheless, opposite effects were observed in TSCC, whereas MAP1LC3B was correlated with SQSTM1 expression in both tumor and adjacent normal tissues in LSCC, suggesting these molecules might be differentially regulated at diverse subsites of OSCC." (PMID 30477228, 2018). "Among these genes, MAP1LC3B played a crucial role in PPI network and was down-regulated in tumor tissues both in TCGA and local cohort." (PMID 40330698, 2025). "Remarkably, patients bearing a tumor characterized by low NKX3-2 and high MAP1LC3B expression (indicative of active autophagy) display a better prognosis." (PMID 40497941, 2025). "The C2-tumor cluster had high autophagy (ATG5, MAP1LC3B), high plasticity (SOX4, CD164) and low mTORC1 activity (RPS6, MLST8), characteristics of early paligenosis (stages 1-2)." (PMID 36788228, 2023). "In this study, we compare protein levels of both MAP1LC3B and SQSTM1 between tumor tissues and corresponding tumor adjacent normal (CTAN) tissues in IDC patients." (PMID 34829743, 2021).